TLR7 (toll like receptor 7)
Diseases named in the same sentence as TLR7 in open-access papers (continued):
Sharing a sentence is not in itself a finding about the gene and the disease.
viral infection (continued). "TLR7-deficient patients do not appear to be susceptible to common viral infections other than SARS-CoV-2, but further studies are required to confirm this." (PMID 36880831, 2023). "Moreover, the mRNA and protein expression levels of TLR7, MyD88, and NF-κB p65 in the lungs of mice were significantly increased after viral infection but significantly downregulated in berberine treatment group." (PMID 37089926, 2023). "TLR7 and 9 are legumain substrates, and thus legumain is involved in diverse functions of the immune system that are dependent on TLR7 and/or 9 signaling, including the immune response to various viral infections." (PMID 36555634, 2022). "The signals that stimulate ABC differentiation are induced via the synergistic engagement of various cytokine and antigenic receptors that are activated during viral infection, including the interferon gamma (IFNγ) receptor, Toll-like receptor 7 (TLR7), and the B cell receptor." (PMID 35298565, 2022). "Certain immunological factors such as microRNAs (miRs), interferon (IFN)-α, IFN-β, and IFN-λ, forced expiratory volume in one second (FEV1), interleukin (IL)-11, nuclear factor-kappa B (NF-κB), and toll-like receptor 7 (TLR7) aid in the pathogenesis that leads to different viral Infections." (PMID 36225449, 2022). "Activation of TLR7 can inhibit viral infection through Th1 immune response, and may also produce bronchiectasis and anti-inflammatory effects." (PMID 36188605, 2022). "In response to viral infection, viral ssRNAis recognized by TLR7." (PMID 35891661, 2022). "Since the activation of TLR7 pathway inhibits viral replication in lungs and reduces airway hyperreactivity triggered by viral infections, synthetic TLR7 agonists [e.g., imiquimod (R837), resiquimod (R848), and 8-hydroxyadenine derivatives] have also been investigated as antiviral drugs." (PMID 36304452, 2022). "Herein, we focused on the early innate cytokine responses in MФ to investigate how TLR7 responsiveness may be modulated during acute virus infection." (PMID 33331816, 2021). "However, the role of TLR7/9 stimulation in B cells during viral infections remains to be elucidated." (PMID 34293057, 2021). "This cohort of patients thus suggests that TLR7 deficiency does not underlie severe disease caused by common viral infections other than SARS-CoV-2, or if so, with lower penetrance." (PMID 34413140, 2021). "Among them, TLR7 is specific to single-stranded RNA, an indicator of viral infection." (PMID 33331816, 2021). "This may support the virus to replicate more easily, which upon re-sensitization of TLR7 signaling due to severe viral infection could result in an overwhelming TLR7 response that may promote the development of severe COVID-19." (PMID 34835108, 2021). "Taken together, engagement of TLR7 post-viral infection may play a role in producing anti-inflammatory cytokines such as IL-10, which could lead to a return to homeostasis by controlling the production of proinflammatory cytokines." (PMID 33331816, 2021). "Since we observed that R848 treatment and the combination of virus infection and R848 treatment modulated cytokine production and TLR7-mediated signalling, we next examined if these parameters could influence TLR7 expression." (PMID 33331816, 2021). "Thus, Tlr7 duplication in DKO males results in hematologic and serologic abnormalities that can be associated not only with SLE but also with severe viral infections like COVID-19." (PMID 34376664, 2021). "Indeed, in somatic cells, TLR7/8 are a part of the innate immune system involved in recognising and combating viral infections." (PMID 32203540, 2020). "Likewise, human myeloid CD1c+ DCs and human pDCs show a similar metabolic reprogramming upon pRNA (TLR7/8) stimulation or viral infection (TLR7), respectively." (PMID 33013685, 2020).
viral infection (continued). "Male BXSB mice possess additional TLR7 and the TMEV RNA genome is the potential ligand for TLR7, so the viral infection might promote autoantibody production via TLR7-mediated triggering." (PMID 32727036, 2020). "Among PRRs, the endosomal TLRs including TLR3, TLR7/8 and TLR9, and cytosolic RLRs including retinoic acid-inducible gene I (RIG-I) and melanoma differentiation-associated gene 5 (MDA5) play important roles in sensing viral RNA during viral infection." (PMID 33679702, 2020). "Umehara and colleagues speculate that TLR7/8 could be activated in response to viral infection either of the male or female reproductive tract." (PMID 32203540, 2020). "Potentially, this signifies Cys98 of TLR7 as a novel redox sensor that may dampen immune function during viral infections." (PMID 32008365, 2020). "Do TLR7/8 take a toll on viral infections in the reproductive tracts?" (PMID 32203540, 2020). "TLR4 and TLR7 are two major TLRs that recognize microbial components during bacterial and viral infections, respectively, and respond to lipopolysaccharide from gram-negative bacteria and single-stranded (ssRNA) from viruses to initiate protective immune responses against pathogens." (PMID 31785145, 2019). "In response to a viral infection, pDCs can recognize viruses through toll-like receptor 7 (TLR7) and toll-like receptor 9 (TLR9) signaling and rapidly produce type I interferons (IFNs), which can lead to robust CD8+ T cell activation and increase antigen presentation on DCs." (PMID 30991681, 2019). "To test this hypothesis, we compared viral infection in the foot skin (site of virus administration) of Wt and TLR7−/− mice." (PMID 30930901, 2019). "In contrast, we find that cell-specific loss of TLR7 in podoplanin+ cells fails to influence early viral infection in dLN." (PMID 30930901, 2019). "In summary, the present study builds upon a wealth of literature that places TLR7 as a critical sensor of viral infection, a powerful antiviral signaling system and thus a strong candidate target for the treatment of respiratory viral infections such as influenza infection." (PMID 30787331, 2019). "This provides a previously unrecognized link between TLR7 and complement during viral infection." (PMID 30992428, 2019). "Therefore, an epidemiological study of the relationship between the sex ratio bias and RNA viral infection would determine if there is such an in vivo function of TLR7/8 in sperm." (PMID 31408454, 2019). "Especially TLR7-mediated responses in pDCs were enhanced after bLF supplementation compared to placebo, suggesting that bLF may contribute to protection against viral infections in elderly women." (PMID 30515164, 2018). "The expression of IRAK4 was low upon viral infection, indicating that the TLR7 knockout might affect IRAK4 expression in the downstream pathway." (PMID 30151032, 2018). "However, neither TCM treatment groups showed any difference compared to the virus control, which indicated that the therapeutic effects of TCM on viral infection induced inflammation needed the participation of TLR7 signaling." (PMID 30151032, 2018). "It’s found that the TLR7 was up-regulated in the macrophages upon virus infection." (PMID 30151032, 2018). "We next investigated the role of Arl8b in TLR7 responses toinfluenza virus infection of pDCs." (PMID 29150602, 2017). "Since IgG2a is known to be the most efficient IgG subclass for viral clearance we investigated whether TLR7 expression in T cells plays a role in B cell responses to viral infection." (PMID 27880772, 2016). "Alternatively, IFN induction during viral infection is possible through TLR7 and TLR9 in DCs." (PMID 28163697, 2016). "Detection of virus infection by pDCs is mediated through recognition of viral nucleic acids, including single-stranded RNA (ssRNA) and double-stranded DNA containing unmethylated CpG motifs by the Toll-like receptor 7 (TLR7) and 9 (TLR9) endosomal sensors." (PMID 26172439, 2015).
viral infection (continued). "Emerging data have identified new and intriguing roles for platelet TLR7 during viral infections." (PMID 25566264, 2014). "This study drew considerable interest, as it would have represented, if confirmed, the first example of a species-specific adaptation to a chronic virus infection that occurs through a genetically determined abrogation of a key innate immune pathway, i.e., the TLR7/9-IRF7-type I IFN pathway." (PMID 24009514, 2013). "TLR7 activation may be particularly suited for the treatment of acute exacerbations of asthma as these are often due to viral infections, and in addition to its potent pro-resolving function, TLR7 also exhibits strong antiviral activity." (PMID 23584892, 2013). "Agonists of TLR3 and TLR7-9 yielded very promising results for treating viral infections." (PMID 24302927, 2013). "In the kidney cortex, perturbation of homeostasis by a TLR7-dependent nucleic acid “danger” signal, which may signify viral infection or local cell death, triggers Gαi-dependent intravascular retention of Ly6Clow monocytes by the endothelium." (PMID 23582326, 2013). "The impaired liver responses observed in 3d mice that were not apparent in TLR9 or TLR7-deficient mice suggests that a level of redundancy unique to innate immunity is in place within infected tissue sites to rapidly respond to viral infection." (PMID 22723955, 2012). "Germinal centers regulate the development of antibodies that protect against viral infection, and manipulation of TLR7 and its signaling pathway in B cells could be a viable strategy for enhancing immunity to viruses." (PMID 21998589, 2011). "The important role of TLR7 in viral infection and immunization prompted us to characterize TLR7 gene polymorphisms in simian immunodeficiency virus (SIV)-infected rhesus macaques (Macaca mulatta), which represent the most important animal model of HIV infection." (PMID 22022401, 2011). "Indeed, in TLR9−/− mice, TLR7 can promote sufficient residual pDC IFN-I production to allow a better control of viral infection and an enhanced resistance to viral-induced lethality as compared to MyD88−/− or TLR7−/−TLR9−/− animals." (PMID 21994554, 2009). "Synthetic ligands mimicking microbial ligands of TLR9 and TLR7 have been generated and used to dissect the molecular pathway downstream of Myd88, but these artificial molecules did not exactly reproduce the signaling cascades induced in pDCs during in vivo viral infections." (PMID 38777879, 2024). "In mice deficient in TLR7/9 or Myd88 or depleted of pDCs and infected with viruses, such as MCMV, HSV or DENV, NK cell cytotoxicity, and cytokine production were decreased or even abolished, thus supporting the contribution of pDCs to NK cell activation in vivo during viral infections." (PMID 38777879, 2024). "In TLR7-deficient mice, Yin-Qiao San failed to inhibit upregulation of NF-κB under viral infection." (PMID 37089926, 2023). "Furthermore, its role in intracellular recognition of nucleic acids has been demonstrated; thus, higher TLR7 expression might provide improved protection against viral diseases." (PMID 37107551, 2023). "Additionally, viral infections have long been considered to be highly associated with SS and may be related to human cytomegalovirus (HCMV)-induced stimulation of TLR7 and TLR9." (PMID 36248435, 2022). "The novelty of this research is that we specifically determined the intracellular signaling pathway in B cells after TLR7 stimulation with IMQ by using proteomics analysis in the SLE animal model in order to determine the pathological role of B cells in SLE patients after viral infection." (PMID 36359746, 2022). "TLR7, a viral nucleic acid pathogen recognition receptor, is located on a region of the X chromosome which is known to have a lower level of chromosomal inactivation, allowing females to have stronger interferon responses during viral infection due to gene dosing." (PMID 34267262, 2021).
viral infection (continued). "Importantly, TLR7 has also been shown to be significantly involved in the development of fully functional adaptive immune reactions, also in the context of vaccination and persistent viral infection." (PMID 29497422, 2018). "Interestingly, AXL is associated with viral infection, TLR7/8 transcript abundance, and STAT2 transcript abundance in placenta cells, since their levels vary both when these cells are infected as well as when TLR7/8 or STAT2 are knocked down." (PMID 30453684, 2018). "Therefore, HRS-mediated TLR7 complex assembly may provide an important mechanism for the regulation of host immune and inflammatory responses during viral infection." (PMID 28854257, 2017). "Although the parasitic ligand triggering TLR7 has not yet been proven, however, based on finding that single-stranded RNA is required for TLR7-dependent production of IFN-I during viral infection, it was hypothesized that the RNA of parasite might work as a ligand against the receptor." (PMID 28400771, 2017). "Thus, eosinophil activation via TLR7 might engender a link between viral infection and allergic exacerbations." (PMID 22857391, 2012). "Perinatal expression of TLR7 in neurons and glia may influence the receptiveness and the responsiveness of the developing brain to viral infections, which in turn may play a role in the etiology of neurodevelopmental disorders including autism and schizophrenia." (PMID 22666391, 2012). "Taken together, our findings of altered TLR7/8 responses with or without endotoxin (LPS) pre-treatment may indicate a predisposition to recurrent viral infections in the ASD test group as compared to ASD and non-ASD case controls." (PMID 19025588, 2008). "Members of the TLR family that have been shown to be involved in responses to viral infection, in part including that of SARS-CoV-2, are TLR1, TLR2, TLR3, TLR4, TLR6, TLR7, TLR8 and TLR9." (PMID 41011507, 2025). "ATRA alone upregulated TLR3, TLR4 and RIG-I intestinal epithelial cells, however it suppressed TLR3, TLR7 and RIG-I expression following viral infections." (PMID 40666513, 2025). "TLR7 and TLR8 are endosomal sensors of single-stranded RNA that play essential roles in the defence against viral infection and in the induction of B cell systemic autoimmunity." (PMID 40336011, 2025). "In wild-type mice, Yinqiao powder significantly decreases the expression levels of TLR7, MYD88, IRAK4, and NF-κB, which are elevated during viral infection." (PMID 39897040, 2025). "TLR7 recognizes ssRNA and induces the production of large amounts of IFN-α and inflammatory cytokines, which are responsible for promoting the control of viral infections." (PMID 39650644, 2024). "TLR-3 and TLR-7 closely interact with STAT-3, which is crucial for regulating cytokine-mediated responses, such as IL-6 to combat viral infections." (PMID 39281683, 2024). "The suppressive effect of viral infection on CD11b+CD11c+ cells is largely mediated by type I IFN that can be triggered by the ligation of innate receptors, including TLR7." (PMID 38732169, 2024). "For instance, TLR7 and TLR9 are often activated in therapies against viral infections and as adjuvants in cancer vaccines, while TLR2 and TLR4 are targeted by antagonists to mitigate inflammatory responses in sepsis and other inflammatory diseases." (PMID 38732254, 2024). "TLR7 recognizes ssRNA derived from influenza virus, whereas the relevance of TLR8 in this viral infection still needs more investigation." (PMID 37089926, 2023). "TLR7 and TLR9 pathway activation is also required for effective responses to vaccines and viral infections, such as COVID-19, which disproportionately affects Black individuals and Hispanics in both frequency and severity." (PMID 37606045, 2023). "The present study raises the possibility that bacterial and viral infection through activation of TLR-3, TLR-4 and TLR-7/8, have the potential to alter fetal brain protection." (PMID 36721242, 2023).
viral infection (continued). "TLR7 and TLR9, whose ligands are ssRNA and dsDNA, respectively, work as innate sensors for detecting viral infections." (PMID 36875095, 2023). "In fact, ssRNA and dsRNA viruses are detectable by TLR7/8 and TLR3, which produce antiviral immune responses by detecting viral infection, activating signaling pathways, and inducing the production of antiviral cytokines and chemokines." (PMID 34659656, 2021). "The levels of TLR3, TLR7, myeloid differentiation primary response 88 (Myd88), and RIG-I were up-regulated due to viral infection, which were decreased, as expected, in the presence of 3D, oseltamivir, or ribavirin." (PMID 33670217, 2021). "CL075, a dual agonist for TLR-7 and TLR-8 that mimics single-stranded RNA, was selected for study given the high burden of viral infections in young children." (PMID 35185860, 2021). "Several immune system components, including TLR7, FOXP3, CD40L, TLR8, and CXCR3, are affected by the X chromosome and can be upregulated in women and impact the response to viral infections." (PMID 34203647, 2021). "TLR7−/− mice lack sufficient type I IFN production in response to acute LCMV-WE infection, indicating that TLR7 can play a crucial role during viral infection." (PMID 33331816, 2021). "In this current study, we identified three immune response molecules, which were earlier known to have immunity against viral infection such as RIGI, TLR7, and TLR3." (PMID 34970593, 2021). "TLR7 and its closely related receptor, TLR8, play an important role in the immune response to viral infection; they recognize single-stranded RNAs as natural ligand but have also been demonstrated to sense imidazoquinolines and nucleoside analogues." (PMID 33578955, 2021). "R848 (resiquimod), a small-molecule compound of imidazoquinoline, is an agonist of TLR7 and TLR8 that is currently used clinically to treat infectious viral diseases and tumours." (PMID 34340711, 2021). "The originality of our work lies in the stimulation of TLR7 and TLR8 which reproduce in vitro a viral infection by the activation of innate immune system and produce type I IFN." (PMID 33585507, 2020). "Cooperation between TLR7 and other viral sensors collectively called RIG-1 like receptors (RLRs) (melanoma differentiation-associated protein 5 [MDA5], laboratory of genetic and physiology 2 [LGP2], retinoic acid inducible gene [RIG]-I), may operate to robustly respond to viral infections." (PMID 32774170, 2020). "TLR-7/8, the most well-known component of the TLR pathway, has also been reported to inhibit viral replication during viral infection through IFNα secretion as well as enhance mucosal immunity and systemic immune response." (PMID 31736952, 2019). "SLC15A4, selectively transcribed in bovine and also in human pDC, was shown to be required for signaling through TLR7 and TLR9 in murine pDC and, as a consequence, for pDC-mediated control of persistent viral infection." (PMID 30425716, 2018). "The propagated importance of pDC for early sensing of viral infection is supported by the high transcription rate of TLR3, TLR7, and TLR9 found in bovine pDC." (PMID 30425716, 2018). "Upon viral infection, type I IFN is mainly produced by plasmacytoid dendritic cells (pDCs) when stimulated through Toll-like receptor 7 (TLR7) and TLR9." (PMID 30210502, 2018). "Subsequent analysis of these data using modern pathway analysis methods revealed that the TLR7/8 pathway was strongly inhibited in HMC3 cells, while it was activated in JEG-3 cells during virus infection." (PMID 30453684, 2018). "We reveal that HRS is important for activation of NF-κB, IκBα, and p38 during viral infections, suggesting that HRS plays critical roles in TLR7-mediated activation of NF-κB, p38 MAPK, and IRF3 pathways." (PMID 28854257, 2017). "Since EV71 induces TLR7 and HRS, the correlation between TLR7 and HRS during viral infection was determined." (PMID 28854257, 2017).